APOE (apolipoprotein E)
Diseases named in the same sentence as APOE in open-access papers (continued):
Sharing a sentence is not in itself a finding about the gene and the disease.
pancreatic cancer (20 papers, 2013 to 2025). "Our observation that Apolipoprotein E (APOE) was the highest-ranking splice variant result for BCNHL resonates with previous findings that associate this gene with pancreatic cancer pathology." (PMID 36873459, 2022). "High expression of APOE is associated with shorter survival in pancreatic cancer patients." (PMID 37958351, 2023). "Apolipoprotein A (APOA) seems to be a good indicator of several cancers, such as colon, hepatocellular, and pancreatic cancer; meanwhile, apolipoprotein E (APOE) may have polymorphisms that affect tumor susceptibility." (PMID 37628784, 2023). "Furthermore, APOE expression was found to be higher in pancreatic cancer tissue than in normal pancreatic tissue, and that elevated APOE levels are linked to worse outcomes for pancreatic cancer patients." (PMID 38067270, 2023). "Conversely, APOE assumes an immunosuppressive role in the pancreatic cancer microenvironment by upregulating the expression of CXCL1 and CXCL540." (PMID 39990672, 2025). "In pancreatic cancer, APOE+ macrophages inhibit CD8 T cell infiltration by producing CXCL1 and CXCL528." (PMID 40835684, 2025). "APOE was found to contribute to immunosuppression and inhibiting the apoptosis of malignant cells in pancreatic cancer." (PMID 38067270, 2023). "According to a recent study, ApoE has a role in pancreatic cancer growth and development in addition to helping cancer cells evade the immune system." (PMID 37623681, 2023). "APOE contributes to immune suppression in pancreatic cancer by activating the NF-κB signaling pathway." (PMID 38067270, 2023). "These properties make ApoE a good candidate as a tumor marker and a chemotherapeutic target in pancreatic cancer." (PMID 37623681, 2023). "In pancreatic cancer, APOE involved the expression of Cxcl1 and Cxcl5, known immunosuppressive factors, leading to immunosuppression." (PMID 35216190, 2022). "In pancreatic cancer, TAMs expressing high levels of APOE exert immunosuppressive effects." (PMID 40678806, 2025). "APOE is elevated in several malignancies including pancreatic cancer." (PMID 24708694, 2014). "Although the underlying mechanisms remain to be fully elucidated in pancreatic cancer models, research has proved that ApoE, DCBLD1 and XRCC1 are significant factors in pancreatic cancer." (PMID 41007358, 2025). "We established and validated a prognostic model for pancreatic cancer with 7 signatures, including ADH1C, APOE, RAP1GAP, NPC1L1, P4HB, SOD2, and TNFSF10." (PMID 38685045, 2024). "Using advanced mass spectrometry-based techniques, it was shown that using a panel of APOA1, APOE, APOL1, and trypsin inhibitor heavy chain H3 (ITIH3) can provide a sensitivity of 95% and specificity of 94.1% in the diagnosis of pancreatic cancer." (PMID 38067270, 2023). "Consistently, ITIH3, which has significant involvement in extracellular matrix remodeling during tumor progression, along with APOA1, APOE, APOL1, and CA19-9, constitutes a biomarker panel for pancreatic cancer." (PMID 37628784, 2023). "Five proteins including CD9, perlecan (HSPG2), apolipoprotein E (APOE), stromal cell derived factor 4 (SDF4), and fibronectin receptor/integrin β1 (ITGB1) were subsequently validated by immunohistochemistry on human pancreatic cancer tissue." (PMID 24708694, 2014).
cerebral microbleeds (19 papers, 2015 to 2025). Cerebral microbleeds are a group of pathological processes affecting the small arteries, arterioles, capillaries and venules of the brain, as detected by brain imaging techniques. "Extending these analyses to cerebral microbleeds, we found that higher genetically determined CSF levels of APOE and APOE2 and lower plasma levels of APOE were associated with increased risk of microbleeds (PFDR < 0.05)." (PMID 41266628, 2025). "This study was performed to investigate the association between urinary Alzheimer-associated neuronal thread protein (AD7c-NTP) with cerebral microbleeds (CMBs) based on the apolipoprotein E (APOE) genotypes." (PMID 34660786, 2021). "Several population-based studies have reported the association between the E4 variant of APOE (APOE ε4) carrier and the presence of cerebral microbleeds, especially in lobar distribution." (PMID 34881076, 2021). "For example, genetic polymorphisms, such as the APOE ε4 allele associated with an increased burden of cerebral microbleeds, as well as those related to lipid metabolism or inflammation could modulate the impact of NHR or the Albumin to Globulin ratio on CMBs risk." (PMID 39734492, 2024). "However, among the MMD group, individuals carrying the ε2 or ε4 alleles exhibited a higher incidence of cerebral microbleeds—an established biomarker of cerebral small vessel disease—suggesting that APOE variants may be linked to specific disease phenotypes or increased disease severity in MMD." (PMID 40365738, 2025). "In this population-based cohort study, we found that an estimated one-fourth of the effect of APOE ε4 on cognition is mediated by structural brain imaging markers, driven mainly by cerebral microbleeds." (PMID 40344552, 2025). "In conclusion, we found that one-fourth of the effect of APOE ε4 on cognition was mediated by structural neuroimaging markers, mainly driven by the presence of cerebral microbleeds." (PMID 40344552, 2025). "In this population-based cohort study, we found that approximately one-fourth of the effect of APOE ε4 on cognition is mediated by structural brain imaging markers, mainly driven by the presence of cerebral microbleeds." (PMID 40344552, 2025). "A number of meta-analyses reported significant APOE genotype effects on volumes of cerebral microbleeds." (PMID 38472178, 2024).
Glucose intolerance (19 papers, 2014 to 2025). Glucose intolerance (GI) can be defined as dysglycemia that comprises both prediabetes and diabetes. "This study demonstrated that the Western diet associated with ovariectomy promotes increased fat mass, basal glucose, glucose intolerance, and plasma insulin in female ApoE KO mice." (PMID 37372993, 2023). "These APOE-related CNS effects occur along with multiple metabolic disturbances: weight gain, adipose tissue accumulation, and glucose intolerance." (PMID 34537055, 2021). "ATM haploinsufficiency results in atherosclerotic lesions in apoE null mice accompanied by insulin resistance and glucose intolerance." (PMID 29152614, 2017). "Atm+/− apoE−/− mice also develop atherosclerosis coupled with hypertension, hypercholesterolemia, glucose intolerance, etc48." (PMID 29152614, 2017). "Perhaps the drive of our dietary model toward atherogenesis and glucose intolerance is so strong as to be beyond the reach of the peptide at the level we employed, which was dosed based on studies in apoE-/- and ob/ob mice." (PMID 25286043, 2014). "Our results have shown deterioration of glucose intolerance in STZ-induced diabetic apoE−/− mice." (PMID 25661015, 2015). "On the basis of it, we further performed a study on whether MIF has an effect on improvement of glucose intolerance of DM apoE−/− mice by GTT." (PMID 25661015, 2015).
cerebral small vessel disease (18 papers, 2013 to 2025). Cerebral small vessel disease is the term currently used to pathological processes that affect the brain parenchymal circulation (arterioles, capillaries, and veins). "Cerebral small vessel disease severity and APOE genotype were specifically associated with the late-onset profile (both p < 0.05)." (PMID 34893031, 2021). "It has also been supported by neuroimaging studies which demonstrated significant APOE-by-sex interaction in the distribution of cerebral hypometabolism and changes in cortical thickness, as well as a higher prevalence of APOE-ε4-associated cerebral small vessel disease in male AD patients." (PMID 34122051, 2021). "Interactions among visit-to-visit mean sdLDL, visit-to-visit sdLDL variability, and APOE genotype influencing cerebral small vessel disease progression." (PMID 35847226, 2022). "This study, therefore, investigated the association between visit-to-visit changes in sdLDL and cerebral small vessel disease (CSVD) progression in older individuals, and the influence of Apolipoprotein E (APOE) genotype on this association." (PMID 35847226, 2022). "Deposition of amyloid appears aggravated in patients with cerebral small-vessel disease, especially in APOE ε4 carriers." (PMID 34660786, 2021).
Hearing impairment (18 papers, 2015 to 2025). A decreased magnitude of the sensory perception of sound. "Some studies have previously reported an association between APOE isoform and hearing loss in candidate gene studies." (PMID 34294723, 2021). "Epidemiological studies have indicated that the presence of one APOE4 allele may increase the risk of ARHL, while the presence of ApoE-ε4 homozygote is associated with more severe hearing impairment and earlier onset." (PMID 40258814, 2025). "Based on this, we hypothesize that in the aging hearing loss mouse model used in this study, the significantly increased expression of ApoE protein in cochlear tissue may indicate a more critical role of the ApoE ε4 allele." (PMID 40638992, 2025). "Individuals carrying the ApoE ε4 allele often exhibit a higher risk of hearing loss in later life." (PMID 40638992, 2025). "Additionally, the expression of ApoE in different types of hearing loss (such as presbycusis, traumatic, or ototoxic hearing loss) may vary, offering new insights for further exploration of ApoE's role in hearing loss." (PMID 40638992, 2025). "Other work suggests the presence of one or more APOEε4 alleles may actually be marginally associated with better hearing in older adults as measured via pure tone audiometry, perhaps because APOE ε4 is more common in Black adults, but hearing loss is more prevalent in White adults." (PMID 35295208, 2021). "Though, the association between the APOE ε4 allele and hearing loss has not been well established yet." (PMID 38792885, 2024). "Fifth, we could not include crucial potential confounders such as APOE ε4, hearing loss, and amyloid β because these were not part of the NHIS-HEALS cohort." (PMID 38568921, 2024). "We investigated haplotype tagging single nucleotide polymorphisms in the N‐acetyltransferase 2 gene and the presence/absence of the apolipoprotein E ε4 allele for association with age‐related hearing loss in a cohort of 265 Caucasian elderly volunteers from Greater Manchester, United Kingdom." (PMID 25155015, 2015).
ischemia (18 papers, 2011 to 2025). A hypoperfusion of the BLOOD through an organ or tissue caused by a PATHOLOGIC CONSTRICTION or obstruction of its BLOOD VESSELS, or an absence of BLOOD CIRCULATION. "The ApoE encodes the apolipoprotein E. Apolipoprotein E is thought to have a deleterious effect on the brain following ischemia." (PMID 41516203, 2025). "In the case of ApoE (encoding apolipoprotein E) expression, it was lower than control values after 2 and 30 days and after 6 months; in the remaining periods after ischemia, the expression was above control values." (PMID 41516203, 2025). "APOE-deficient mice exerted more neural death and decreased white matter integrity and cognitive function after chronic cerebral hypoperfusion, which suggests a protect effect of APOE in ischemia." (PMID 39766455, 2024). "ApoE deficient mice have greater cell death, axonal pathology, and behavioral deficits after brain injury, and apoE infusion reduces neuronal cell death in experimental ischemia." (PMID 29618365, 2018). "Moreover, P-ADSCs were implanted into apolipoprotein E (Apo E)-deficient mice with hind limb ischemia." (PMID 26204963, 2015). "Perivascular ApoE deposits were revealed to co-localize with amyloid precursor protein epitopes after ischemia." (PMID 41516203, 2025). "In the studied model of cerebral ischemia, intra- and extracellular ApoE deposits were present in the cerebral cortex 3 h after ischemia and were often visible even a year later." (PMID 41516203, 2025). "On 7 and 30 days and 0.5 years post-ischemia, there was a decline in the expression of ApoE below the control level, and during the remaining observation times, it exceeded the control values." (PMID 41516203, 2025). "In mouse models of hindlimb ischemia using ApoE−/− mice, ApoE was reported to be necessary for mitochondrial function, macrophage infiltration, and muscle healing." (PMID 38074327, 2023). "Similar benefits were also found by others, where intraventricular infusion of ApoE improved global ischemia-induced acute brain injury in ApoE-/- mice." (PMID 30373276, 2018). "ApoE-/- mice are in general more vulnerable to oxidative stress, excitotoxic injury and ischemia, due, at least in part, to their inherently impaired antioxidant mechanisms." (PMID 29541261, 2018). "Maximum ApoJ expression 1 year after ischemia is associated with increasing and progressive neuronal death and ineffective elimination of the negative effects of ApoE activity." (PMID 41516203, 2025). "Indeed, our results show that the ischemia-induced level of endogenous neurogenesis in ApoE3-TR mice was higher compared with ApoE4-TR mice and may reflect the impact of a HF diet and specific ApoE background on the ischemia-induced motor deficits." (PMID 23957944, 2013). "When delivered intra-arterially into the ischemic hindlimbs of ApoE−/− mice, CD34+/M-cad+ BMCs alleviated ischemia and significantly improved blood flow compared with CD34+/M-cad− BMCs, CD34−/M-cad+ BMCs, or unselected BMCs." (PMID 21677770, 2011).
lupus (18 papers, 2010 to 2025). "Pristane-induced lupus-like manifestations in ApoE-/- mice were associated with significant elevations in serum anti-dsDNA and ANA levels during disease progression." (PMID 40867523, 2025). "Subsequently, it was demonstrated that global heterozygous deficiency of IRF5 also reduces disease in the Lyn-deficient mouse lupus model, the gld.apoE-deficient mouse lupus model, and in the Swap70-deficient Def6-deficient mouse lupus model." (PMID 34197340, 2021). "For example, ApoE deficient lupus mouse models are known to have both splenomegaly and B lymphocyte alterations." (PMID 26503550, 2015). "Among existing approaches, the induction of lupus via pristane injection in ApoE-/- mice remains a widely utilized method for generating SLE-AS models." (PMID 40867523, 2025). "We assessed the extent of renal damage associated with the lupus phenotype, in control versus the MMF treated experimental gld.apoE−/− group." (PMID 23577189, 2013). "We first compared lupus symptoms in ApoE−/−Fas−/− mice with B6 mice." (PMID 35850768, 2022). "Furthermore, the apoE−/−Fas−/− mice were transplanted with MSCs and lupus-like autoimmunity and atherosclerotic lesions were assessed." (PMID 35850768, 2022). "Apolipoprotein E (APOE) and alpha-1-antichymotrypsin (SERPINA3) were both reported to positively correlate with cardiovascular events and lupus activity." (PMID 41614843, 2025). "In CD5+ B-1 cells obtained from aged male ApoE knockout mice, the most frequently utilized CDR-H3 is AGDYDGYWYFDV (VH12/DH2/JH1), which is the same frequently utilized CDR-H3 seen in the lupus-prone mice." (PMID 36713434, 2022). "The ApoE−/−Fas−/− mice displayed the hallmarks of lupus, including high titers of anti-dsDNA antibodies, proteinuria, creatinine, and increased IgG and IgM in serum, which resembled prominent features of human SLE." (PMID 35850768, 2022).
hyperlipoproteinemia (17 papers, 2009 to 2025). An elevated concentration of lipoproteins. "Atmicroscopy, LPG is characterized by intra-glomerular lipoprotein thrombi andtype III hyperlipoproteinemia due to heterozygote mutation of ApoE gene." (PMID 30421781, 2019). "Both the Apoe Christchurch mutation and e2 homozygosity are associated with Type III hyperlipoproteinemia and lipid metabolism could potentially be an APOE-related protective mechanisms against significant tau accumulation." (PMID 36597122, 2023). "Based on the evidence of human kindreds with inherited apoE deficiency who developed xanthomatosis and type III hyperlipoproteinemia with elevated cholesterol, two independent laboratories developed apoE-deficient mice." (PMID 30037080, 2018). "APO E gene – Apolipoprotein E and hyperlipoproteinemia or hyperlipidemia type III." (PMID 30345000, 2017). "APOE ɛ2 is indeed limited in its ability to mediate the vascular clearance of cholesterol metabolites and triglycerides that could in turn precipitate the risks of cholesterol pathologies such as hyperlipoproteinemia and cardiovascular sequelae." (PMID 36512526, 2022). "In hypothyroidism, the VLDL and IDL particles are high in cholesterol and apolipoprotein E, mimicking the -VLDL particles seen in type III hyperlipoproteinemia." (PMID 35186143, 2022).